BRCA1 (BRCA1 DNA repair associated)
Diseases named in the same sentence as BRCA1 in open-access papers (continued):
Sharing a sentence is not in itself a finding about the gene and the disease.
gastric cancer (continued). "Disease-free survival was significantly decreased with reduced BRCA1 expression (p = 0.027), suggesting that negative BRCA1 nuclear expression could be a predictive marker for the stratification of sporadic gastric cancer patients, who would be good candidates for the adjuvant chemotherapy." (PMID 37568604, 2023). "Therefore, the present study was to investigate whether the genes ERCC1, BRCA1, TYMS, RRM1, TUBB3, STMN1 and TOP2A are underlying biomarkers for patients with gastric cancer, which, to our knowledge, has not been performed." (PMID 28056823, 2017). "Markers useful for therapeutic decision not included in this panel are BRCA1 and BRCA2, important predictive indicators for breast, ovarian, and gastric cancers." (PMID 32340363, 2020).
endometrial cancer (99 papers, 2004 to 2026). Primary or metastatic malignant neoplasm involving the endometrium (mucous membrane that lines the endometrial cavity). "Literature also indicates that there is no conclusive evidence establishing a strong association between endometrial cancer and BRCA1-2 mutations, except for a slight increase in the risk of serous endometrial cancer in BRCA1-mutated carriers." (PMID 41463165, 2025). "Studies that evaluated the relevance of BRCA1/2 mutations in individuals with uterine and endometrial cancer were all included." (PMID 38297203, 2024). "These BRCA1-associated endometrial cancers are associated with an unfavorable outcome and it requires additional studies to confirm these findings." (PMID 38297203, 2024). "In this analysis, 209 patients with BRCA1/2 variants reported in 14 studies were diagnosed with endometrial cancer." (PMID 39061183, 2024). "There is one case–control study that investigated the association between use of HRT and endometrial cancer risk in BRCA1/2-pV carriers." (PMID 39259360, 2024). "An open question is that of endometrial cancer (EC) risk in patients with BRCA1/2 mutation to justify prophylactic hysterectomy during RRSO surgical procedures." (PMID 36837501, 2023). "A total of 1613 endometrial cancer patients from 11 studies were tested for BRCA1/2 pathological variants." (PMID 35683509, 2022). "One study demonstrated an increased risk of developing aggressive and serous-like endometrial cancer, especially in BRCA1 mutation carriers." (PMID 35683509, 2022). "A recent meta-analysis, including 13,871 BRCA1/2 mutation carriers, evaluating the prevalence of endometrial cancer reported a slightly increased risk, mainly for BRCA1, but the absolute risk remained low." (PMID 35267543, 2022). "Progestin-only HRT was associated with a significant increase in endometrial cancer risk (OR = 16.5; 95% CI 2.02–134 P = 0.009) in BRCA1 mutation carriers." (PMID 33885953, 2021). "Regarding endometrial cancer risk associated with HRT use in BRCA1/2 mutation carriers, we found only one publication." (PMID 33885953, 2021). "BRCA1 mutation increased endometrial cancer (RR 5 [3.06–8.16]) and Hodgkin’s disease (RR 3.79 [1.97–7.28])." (PMID 34577828, 2021). "There are some studies which suggest a higher risk of endometrial cancer in BRCA1/2 mutation carriers." (PMID 33885953, 2021). "In conclusion, there is insufficient evidence on the effect of HRT on ovarian and endometrial cancer in BRCA1/2 mutation carriers." (PMID 33885953, 2021). "A multinational cohort study of the Breast Cancer Linkage Consortium involving 11,847 BRCA1 variant carriers reported a significant two-to-three-fold increase in the risk of endometrial cancer." (PMID 32854222, 2020). "We were able to include data on BRCA1/2 pathogenic variant status of first-degree relatives of women who developed endometrial cancer and of unselected serous endometrial cancer cases to corroborate our findings." (PMID 32698099, 2020). "The largest study to date, conducted across 11 different countries, however, yielded contradictory results, noting a significantly increased risk of endometrial cancer in BRCA1 pathogenic variant carriers and those exposed to tamoxifen." (PMID 32698099, 2020). "The latest international prospective cohort study showed that risk of endometrial cancer is higher in BRCA1 mutation carriers than in the general population." (PMID 24346708, 2014). "The relationship between BRCA1 and BRCA2 genes mutations and the risk of endometrial cancer is controversial and less clear than the role of BRCA1 and BRCA2 in hereditary breast and ovarian/primary peritoneal cancers." (PMID 22518164, 2012). "Few studies provide evidence of an increased risk of endometrial cancer in BRCA1/2-pV carriers." (PMID 39259360, 2024). "The fact that BRCA1 variant carriers may use tamoxifen, which is known to raise the risk of endometrial cancer." (PMID 38297203, 2024).
endometrial cancer (continued). "Does hormone replacement therapy (HRT) influence endometrial cancer risk in BRCA1/2-pV carriers?" (PMID 39259360, 2024). "In a systematic review that intended to summarize the findings of all published studies on the prevalence of BRCA1/2 mutation in patients with endometrial cancer, a total of 1613 patients enrolled into 11 clinical studies were tested for BRCA1/2 mutations and were included in the analysis." (PMID 39061183, 2024). "Germline mutations in BRCA1/2 are detected in 1% endometrial cancer." (PMID 36836017, 2023). "Indeed, for a woman with brain metastases of endometrial cancer origin and with a circulating BRCA1 mutation, treatment with a PARP inhibitor provided an excellent response in brain localizations." (PMID 36980614, 2023). "Among carriers of germline mutations in BRCA1/2 genes, the absolute risk of developing endometrial cancer up to 75 years of age is 3% (similar to life risk in the general population—2.9% (strength of evidence V)), and for the serous type, 1.1% (strength of evidence IIIA)." (PMID 36836017, 2023). "Overall, 1613 endometrial cancer patients from 11 cohorts were tested for BRCA1/2 mutation." (PMID 35683509, 2022). "Germline mutations in BRCA have been associated with cases of endometrial cancer, mainly in BRCA1." (PMID 35428225, 2022). "Therefore, more corroborating data and precision around endometrial cancer risk are needed before hysterectomy in BRCA1 or BRCA2 carriers can be routinely advocated." (PMID 34672090, 2022). "Risk for endometrial cancer in BRCA1/2 mutation carriers is being discussed controversially." (PMID 33885953, 2021). "There were only two BRCA1 mutation carriers diagnosed with endometrial cancer who were exposed to ET and analyses associated with monotherapy could not be performed in BRCA2 mutation." (PMID 33885953, 2021). "The biological functions of TopBP1 protein as well as its close similarity with BRCA1 prompted us to investigate whether alterations in TopBP1 gene can influence the risk of endometrial cancer." (PMID 24346708, 2014). "The results showed that ATR and BRCA1 were frequently mutated in endometrial cancer patients." (PMID 24346708, 2014). "Likewise, the authors also reviewed the incidence of endometrial cancer in patients with BRCA1/2 pathogenic variants, knowledge that should help patients and surgeons alike consider conducting a hysterectomy at the time of salpingo-oophorectomy for such patients." (PMID 39061183, 2024). "Moreover, a study has suggested an association between BRCA1 and serous endometrial cancer subtype." (PMID 37682500, 2024). "This study, therefore, sought to determine whether BRCA pathogenic variants are associated with an increased risk of endometrial cancer compared with the general population using a large, well-described cohort of BRCA1 and BRCA2 pathogenic variant carriers with prospective follow-ups." (PMID 32698099, 2020). "Previous studies have mainly focused on endometrial cancer risks in individuals with BRCA1/2 GPV, particularly after RRSO." (PMID 40427184, 2025). "The purpose of this study was to identify the clinical features of endometrial cancers (EC) with microsatellite instability-high (MSI-H) and BRCA1/2 mutations (BRCAm)." (PMID 41426330, 2025). "BRCA1/2 were identified in 70 (4.3%) women with endometrial cancers, while BRCA1 was identified in 71.4% of the patients." (PMID 39061183, 2024). "In this cohort study of 1,083 women, there were five incident cases of serous/serous-like endometrial carcinoma that occurred after RRSO, four in BRCA1 mutation carriers, and one in BRCA2 mutation carriers." (PMID 38297203, 2024).
endometrial cancer (continued). "A total of 209 BRCAm carriers from 14 studies diagnosed with BRCA1/2m were diagnosed with endometrial cancer." (PMID 35683509, 2022). "BRCA1 and BRCA2 mutations were put together for analysis; most studies were case-control studies, and cases were selected amongst patients with endometrial carcinoma." (PMID 34577828, 2021). "The ESMO clinical practice guidelines for cancer prevention and screening in BRCA mutation carriers report that the association between BRCA1/BRCA2 mutations and an elevated risk of endometrial cancer remains weak." (PMID 32655641, 2020). "Fourteen cases of endometrial cancer were identified in 2609 women (1350 BRCA1 and 1259 BRCA2), of which two were prospectively diagnosed." (PMID 32698099, 2020). "The BRCA1 deletion 9-19, identified in a proband that developed breastcancer at the age of 41 and endometrial cancer at the age of 44 years has been describedin an Italian patient." (PMID 27303907, 2016). "We identified germline mutations in BRCA1 and in MSH6 in a patient with increased risk for HBOC diagnosed with endometrial cancer at the age of 46 years." (PMID 23164213, 2012). "In p53abn endometrial cancer, 25% of patients show HRD and <5% harbor BRCA1/2 mutations." (PMID 41583426, 2025). "Interestingly, the BRCA1 and BRCA2 variants also were associated with high grade of endometrial carcinoma in the identified carriers." (PMID 39400928, 2025). "A correlation between BRCA1/2 P/LP variants and endometrial cancer was reported in only five of the 14 studies; such a correlation was related to the BRCA1 variant and not to BRCA2 in two studies." (PMID 39061183, 2024). "The impact of HRT on endometrial cancer risk in BRCA1/2-pV carriers has not been sufficiently investigated." (PMID 39259360, 2024). "The risk of endometrial cancer in women with P/LP BRCA1 or BRCA2 variants is not well characterized." (PMID 39061183, 2024). "In addition to well-known cancer-gene associations, we also identified that P/LP variants in BRCA1 (OR, 5.47; 95% CI, 1.42-17.17; P = .008) and FANCI (OR, 5.53; 95% CI, 1.03-19.47; P = .02) were associated with endometrial cancer." (PMID 37523182, 2023). "A previous analysis of 1083 women who underwent RRSO without hysterectomy revealed that although the overall risk for uterine cancer after RRSO was not increased, the risk for serous/serous-like endometrial carcinoma was increased in BRCA1 pathogenic women." (PMID 36849964, 2023). "BRCA1/2m were identified in 70 women with endometrial cancer out of 1613 (4.3%)." (PMID 35683509, 2022). "BRCA1/2m were identified in 4.3% of women with endometrial cancer (70/1613)." (PMID 35683509, 2022). "Surveillance and prevention of endometrial cancer in BRCA1 mutation carriers are not advised by the Belgian Society of Human Genetics, because the cumulative risk of serous endometrial cancer is less than 5% at 70 years of age." (PMID 32655641, 2020). "In addition, PVs in BRCA1, BRCA2, and NBN were significantly associated with moderately increased risks for uterine/endometrial cancer." (PMID 31406321, 2020). "In one study of 199 Ashkenazi Jewish patients with endometrial cancer, the frequency of germ-cell line BRCA1 and BRCA2 mutations (3 per 199, 1.5%) in endometrial cancer patients was comparable to the baseline rate of 2% in the Ashkenazi population, suggesting no increased risk." (PMID 22518164, 2012).
endometrial cancer (continued). "Moreover, the number of reported serous endometrial cancer cases are small, confidence intervals wide, and the absolute lifetime risk is low (around 3%), and total endometrial cancer risk is not increased in BRCA1 carriers." (PMID 34672090, 2022). "Interestingly, PABC subjects #964 and #749 were identified to have the same pathogenic mutation (BRCA1: c.3700_3704delGTAAA), however the former has no reported family history, while the latter has a family history of breast and endometrial cancer." (PMID 34011307, 2021). "•Endometrial cancer risk was not increased in BRCA1/2 pathogenic variant carriers." (PMID 32698099, 2020). "Of the 4893 women studied, 3536 were BRCA1 pathogenic variant carriers, explaining why there was no statistically significant increase in endometrial cancer risk in the BRCA2 group, despite similar SIRs (BRCA1 SIR = 1.91, 95% CI = 1.06–3.19, p = 0.03, BRCA2 SIR = 1.75, 95% CI = 0.55–4.23, p = 0.2)." (PMID 32698099, 2020). "Debate, therefore, continues within the scientific and medical communities as to whether risk-reducing hysterectomy should be offered to women with BRCA1 and BRCA2 pathogenic variants at the time of their RRSO to reduce their subsequent endometrial cancer risk." (PMID 32698099, 2020). "Since the publication of a number of reports describing diagnoses of serous endometrial cancer in BRCA1 pathogenic variant carriers of Ashkenazi Jewish heritage, there has been interest in a potential association between the BRCA pathogenic variants and an increased risk of endometrial cancer." (PMID 32698099, 2020). "Similarly, over 11% of the positive findings among women with endometrial cancer were in BRCA1/2." (PMID 26681312, 2016). "Thus it seems that screening for endometrial cancer is not warranted in known BRCA1 or BRCA2 mutations carriers." (PMID 22518164, 2012). "There was a single case of a triple heterozygote (BRCA1/MLH1/MSH6; case 69) who developed endometrial cancer at age 41 years." (PMID 39843919, 2025). "However, BRCA1 mutation may increase risk for serous subtype of endometrial cancer but not endometrioid subtype." (PMID 34048176, 2021). "In summary, these data emphasize the notion that tumor suppressor BRCA1 is involved in controlling the expression and action of the IGF axis in endometrial cancer." (PMID 24904527, 2014). "In another study, 857 known BRCA1 and BRCA2 carriers aged 45 to 70 were followed over time for the development of endometrial cancer." (PMID 22518164, 2012). "This study revealed that there was no significantly higher risk of endometrial cancer in BRCA-mutation carriers, and despite some literature suggesting an association between BRCA1 and serous endometrial cancer, this study does not reinforce this association." (PMID 37682500, 2024). "In 2016, the overall risk for uterine cancer after RRSO did not increase, whereas that for serous/serous-like endometrial cancer (EC) increased in women with BRCA1 PVs18." (PMID 36658289, 2023). "In conclusion, BRCA1 and BRCA2 pathogenic variant carriers do not appear to be at a significant increased risk of endometrial cancer compared with the general population." (PMID 32698099, 2020). "Some data suggest a slightly increased risk of endometrial cancer in BRCA carriers, with more evidence for a correlation with BRCA1 and then with BRCA2; however, the risk is not clearly defined." (PMID 32655641, 2020). "BRCA1 and 2 account for 14.1% of non-mucinous ovarian cancers, 17% of serous cancers and 3% of endometrial cancers in Australia." (PMID 28936272, 2017). "However, it is not clear if BRCA1 and BRCA2 mutations also provide increased lifetime risk of endometrial cancer (EC)." (PMID 36837501, 2023).
endometrial cancer (continued). "In addition, the ability of YTHDC1 to splice transcripts has been demonstrated for a vascular endothelial growth factor (VEGF), breast cancer 1 (BRCA1), and the progesterone receptor (PGR) in endometrial carcinoma, but whether these processes are dependent on m6A modification is still unclear." (PMID 33795663, 2021). "Cohorts enriched with patients fulfilling either the NCCN guidelines for HBOC, LS or society of gynecological oncology criteria for endometrial cancer display lower positive rates for “non-BRCA” and “non-LS genes” relative to the BRCA1/2 and LS genes." (PMID 29308099, 2018).